DLG2 (discs large MAGUK scaffold protein 2)
Diseases named in the same sentence as DLG2 in open-access papers (continued):
Sharing a sentence is not in itself a finding about the gene and the disease.
neurodevelopmental disorder (7 papers, 2015 to 2025). A behavioral and cognitive disorder with onset during the developmental period that involves impaired or aberrant development of intellectual, motor, or social functions. "Co‐clinical trials are also applicable to rare neurodevelopmental disorders associated with variants in the DLG2 gene, as illustrated in the studies analyzed, following a line inspired by strategies previously adopted in genetic syndromes such as APL." (PMID 41236438, 2025). "Rare disruptive DLG2 gene variants are associated with a variety of neurodevelopmental disorders, including schizophrenia, intellectual disability ADHD, and autism spectrum disorder, as well as with bipolar disorder." (PMID 35205368, 2022). "While DLG4/PSD-95 has been extensively studied with respect to its association with neurodevelopmental disorders, the results of the present study suggest a potential role for DLG2/PSD-93 in ASD as well." (PMID 32164788, 2020). "Despite emerging evidence of its implication in psychiatric and neurodevelopmental disorders, it remains unclear the mechanism by which a DLG2/PSD-93 plays a pathological role." (PMID 35966008, 2022). "Given that DLG2 is highly abundant in the striatum during early development in both human and mouse brains, these findings provide clues that may help elucidate the involvement of DLG2 in neurodevelopmental disorders, including ASD, potentially through its influence on striatal circuits." (PMID 32164788, 2020).
neurodegenerative disease (3 papers, 2017 to 2023). A disorder of the central nervous system characterized by gradual and progressive loss of neural tissue and neurologic function. "In contrast to DLG1, there is less evidence to suggest that DLG2 is contributing to CSVD/neurodegenerative disease." (PMID 37422595, 2023). "The other five genes, bound by Tau under HS conditions (as also Grm5), were chosen according to their implication in neurodegenerative diseases (Trex1, Dlg2, Dlg1, Xrcc6, Eif2a)." (PMID 30321409, 2018). "This evidence suggested that DLG2 and ASCC3 might have pleiotropic effects on putamen and neurodegenerative diseases; on the other hand, they might influence neurodegenerative diseases through alteration of putamen." (PMID 29147026, 2017).
neurological disorders (3 papers, 2022 to 2023). "Like the previous comparison, several of these transcripts, such as CELF5, DEPTOR, DLG2, OPTN and STX3, have been linked to brain functions and neurological disorders, supporting the fact that these hnRNP proteins can work in a network to regulate at least specific sets of targets." (PMID 36267332, 2022). "Furthermore, it was discovered that several targets, such as DLG2, ETV5, PGM3, and ALPK1, were key regulators of neurological diseases." (PMID 36644780, 2023). "Given that corticostriatal circuitry is strongly implicated in cognitive and motor function, these findings provide clues that may help unveil the pathological role of DLG2/PSD-93 in psychiatric and neurological disorders involving dysregulation of striatal circuits." (PMID 35966008, 2022).
brain disorder (1 paper, 2022). A disease affecting the brain or part of the brain. "Here, we present findings that a DLG2/PSD-93 deficiency causes deficits in excitatory synapses, in particular of SPNs in the striatum, and consequent dysfunction of corticostriatal neurotransmission, highlighting the potential role of DLG2 in brain disorders linked to striatum-related circuitries." (PMID 35966008, 2022).
DLG2 also shares sentences with these, for which no sentence is quoted: Cognitive impairment (6 papers); bipolar disorder (5); Parkinson disease (4); acute myeloid leukemia (1); Alpha-thalassemia (1); Aphasia (1); astrocytoma (1); attention deficit-hyperactivity disorder (1); basal cell carcinoma (1); behavioral disorders (1); bladder cancer (1); bone tumors (1); carcinosarcoma (1); Cerebral ischemia (1); childhood asthma (1); Chronic colitis (1); colitis (1); colorectal tumors (1); dependence (1); developmental delay (1); diabetes (1); eating disorder (1); episodic ataxia (1); heroin addiction (1); hippocampal atrophy (1); ischemia (1); language delay (1); lung adenocarcinoma (1); lung carcinoma (1); lung squamous cell carcinoma (1).
A further 12 diseases each share a sentence with DLG2 in 1 paper.